STEAP2 (STEAP2 metalloreductase)
Diseases named in the same sentence as STEAP2 in open-access papers (continued):
Sharing a sentence is not in itself a finding about the gene and the disease.
glioma (3 papers, 2021 to 2022). A benign or malignant brain and spinal cord tumor that arises from glial cells (astrocytes, oligodendrocytes, ependymal cells). "Similar to glioma, STEAP2 expression was low in tumor tissues of other cancers and reflected a positive prognosis, which was consistent with previous findings." (PMID 36060273, 2022). "The 1p/19q codeletion is a crucial marker for the measurement of glioma malignancy, and the 1p/19q codeletion group had a higher STEAP2 level." (PMID 36060273, 2022). "To further confirm the function of STEAP2 in glioma, we evaluated the correlation of STEAP2 with the clinicopathological parameters of different grades of glioma using GEPIA." (PMID 36060273, 2022). "We then divided the samples into three groups according to WHO glioma grading and found that STEAP2 expression levels decreased with increasing glioma grade." (PMID 36060273, 2022). "High expression of STEAP2 prolonged the OS of glioma patients." (PMID 36060273, 2022). "High expression of STEAP2 improved the OS of glioma patients." (PMID 36060273, 2022). "Interestingly, a strong positive correlation of STEAP1 and STEAP2 average expression of pan-cancer was identified in our study including glioma and other different tumor tissues." (PMID 35313641, 2022). "The function of STEAP2 in immune infiltration was not thoroughly explored, and STEAP2 staining of clinical samples could further demonstrate the downregulation of STEAP2 expression in glioma." (PMID 36060273, 2022). "However, the functional role of STEAP1 and STEAP2 in glioma has not yet been established." (PMID 33790946, 2021).
hepatocellular carcinoma (3 papers, 2024 to 2025). A malignant tumor that arises from hepatocytes. "Simultaneously, elevated STEAP2 levels are observed in hepatocellular carcinoma, where STEAP2 facilitates HCC cell motility and invasion by enhancing copper levels and activating certain proteins." (PMID 40433591, 2025). "Notably, it has been established that STEAP2 influences ROS levels and metal homeostasis, leading to MAP kinase signaling in hepatocellular carcinoma." (PMID 41101505, 2025).
lung carcinoma (3 papers, 2021 to 2022). "Considering the possible association between STEAP1 and STEAP2, STEAP1 and STEAP2 seem to be significantly co-expressed in 59 cancer cell lines, but are significantly negatively correlated in lung cancer." (PMID 35346237, 2022). "The results of previous studies and the analysis results of this study suggest that STEAP1 and STEAP2 may be potential diagnostic markers of lung cancer, which can provide a basis for the prognostic assessment of lung cancer." (PMID 35346237, 2022). "STEAP1 and STEAP2 are expected to be potential diagnostic and prognostic markers for lung cancer, which may provide more accurate prognostic indicators for lung cancer." (PMID 35346237, 2022). "Specifically, the high expression of STEAP1 in patients with stage I lung cancer was associated with poor prognosis, and the low expression of STEAP2 in patients with stage I lung cancer was associated with poor prognosis, both of which were statistically significant (P < 0.05)." (PMID 35346237, 2022). "Analysis of the Oncomine database and GEPIA showed that STEAP1 was upregulated and STEAP2 was downregulated in lung cancer tissue, and both expressions were related to the clinical stage of lung cancer." (PMID 35346237, 2022). "The purpose of this study was to evaluate the expression and prognostic value of STEAP1 and STEAP2 in patients with lung cancer." (PMID 35346237, 2022). "The KM curve showed that the downregulation of STEAP1 expression and upregulation of STEAP2 expression were related to a good lung cancer prognosis." (PMID 35346237, 2022). "In summary, this study focused on the expression of STEAP1 and STEAP2 in lung cancer and evaluated their clinical and prognostic value." (PMID 35346237, 2022). "Real-time quantitative polymerase chain reaction, western blotting, and immunocytochemistry were used to evaluate the expression of STEAP1 and STEAP2 in three lung cancer cell lines and normal lung epithelial cell lines." (PMID 35346237, 2022). "We also compared STEAP1 and STEAP2 transcriptional levels between lung cancer and normal tissues using GEPIA." (PMID 35346237, 2022). "This study showed that STEAP1 protein overexpression was significantly correlated with poor prognosis of lung cancer, and STEAP2 protein downregulation was significantly correlated with poor prognosis of lung cancer." (PMID 35346237, 2022). "We adopted bioinformatics methods to systematically and comprehensively analyze the expression level and possible prognosis of STEAP1 and STEAP2 in lung cancer." (PMID 35346237, 2022). "The expression of STEAP2 was negatively correlated with the migration and invasion abilities of lung cancer cells." (PMID 35346237, 2022). "The expression of STEAP2 decreased gradually with an increase in the invasion ability of lung cancer cells." (PMID 35346237, 2022). "Our findings provide new evidence for the role of STEAP2 in lung cancer at the molecular level." (PMID 35346237, 2022). "In addition, we used GEPIA to analyze the relationship between STEAP1 and STEAP2 mRNA levels and lung cancer staging." (PMID 35346237, 2022). "However, at present, there are relatively many studies on the role of STEAP1 in the occurrence and development of cancer, but the pathogenesis of STEAP2 in lung cancer is still unclear." (PMID 35346237, 2022). "However, there are some gaps in our research; as such, more studies are needed to elucidate the molecular mechanisms of STEAP1 and STEAP2 in lung cancer." (PMID 35346237, 2022). "The expression of STEAP1 and STEAP2 in lung cancer cells was consistent with that in tissues." (PMID 35346237, 2022). "Experimental verification showed that, compared with normal lung tissue and epithelial cells, the expression of STEAP2 was downregulated in lung cancer tissue, and STEAP2 was related to the pathological stage, lymph node metastasis, and histological grade of lung cancer." (PMID 35346237, 2022).
lung carcinoma (continued). "Therefore, the purpose of this study was to investigate the expression of STEAP1 and STEAP2 and their potential prognostic value in order to provide a basis for new strategies for the treatment of lung cancer." (PMID 35346237, 2022). "Although abnormal expression of the STEAP family has been reported in a variety of cancers, the expression and prognostic value of STEAP2 in lung cancer remains unclear." (PMID 35346237, 2022). "However, there are few studies on the correlation between STEAP2 and other cancers, and there are currently few studies on the correlation between STEAP2 and lung cancer." (PMID 35346237, 2022). "The prognosis of lung cancer patients with high expression of STEAP2 was significantly better than that of lung cancer patients with a low expression of STEAP2 (HR 0.8 [95% confidence interval 0.68–0.94]; log-rank P = 0.0074) and STEAP2, suggesting poor patient prognosis." (PMID 35346237, 2022). "Compared with the recognized classical markers of lung cancer, STEAP1 and STEAP2 have obvious advantages." (PMID 35346237, 2022). "However, the current research on STEAP2 is still in the preliminary stage, and few studies have focused on the prognostic value of STEAP1 and STEAP2 in lung cancer." (PMID 35346237, 2022). "However, STEAP2 expression is not synchronized across cancers, and there are no data to suggest that STEAP2 expression levels differ in lung cancer." (PMID 35346237, 2022). "Therefore, our controversial result that STEAP1 is negatively correlated with STEAP2 expression level in lung cancer may not be a “real” controversy, and further studies are still needed to clarify." (PMID 35346237, 2022). "The expression and prognosis of STEAP1 and STEAP2 in patients with stage II and III lung cancer were not statistically significant (P >0.05)." (PMID 35346237, 2022).
lymph node metastasis (3 papers, 2022). "Low STEAP2 expression was negatively correlated with high clinical stage and positive lymph node metastasis in patients." (PMID 35346237, 2022). "However, increased expression of STEAP2 positively correlated with lymph node metastasis, distance metastasis and poor differentiation in patients with osteosarcoma." (PMID 36316642, 2022). "In addition, STEAP2 was observably lowly expressed in patients with lymph node metastasis." (PMID 35436987, 2022).
osteosarcoma (3 papers, 2022 to 2024). A usually aggressive malignant bone-forming mesenchymal neoplasm, predominantly affecting adolescents and young adults. "Here, we show that osteosarcoma tissues overexpress STEAP2 and that this is positively linked to poor clinical outcomes in these patients." (PMID 36316642, 2022). "In conclusion, STEAP2 is upregulated in osteosarcoma tissues and exhibits a positive correlation between its expression and the development of malignant osteosarcoma phenotypes and poor patient outcomes." (PMID 36316642, 2022). "The results revealed that the upregulation of STEAP2 in osteosarcoma tissues positively correlated with both the malignant osteosarcoma phenotype and poor patient outcomes." (PMID 36316642, 2022). "This was then validated by the fact that overexpression of STEAP2 in EFEMP2 shRNA-transfected osteosarcoma cells increases the invasive capacity of these cells even in the absence of EFEMP2." (PMID 36316642, 2022). "Our data, thus, suggest that EFEMP2 partly targets STEAP2 to promote osteosarcoma progression by inducing EMT via the PI3K/AKT/mTOR axis." (PMID 36316642, 2022). "We found that inhibition of STEAP2 or Akt expression via RNA interference prevents osteosarcoma cell invasion induced by the endogenous or exogenous overexpression of EFEMP2." (PMID 36316642, 2022). "Taken together, these findings indicate that EFEMP2 likely regulates EMT and activates the PI3K/AKT/mTOR axis by targeting STEAP2, thereby facilitating osteosarcoma cell infiltration and migration." (PMID 36316642, 2022). "Quantitative comparisons of cellular migration and invasion revealed that STEAP2 knockdown inhibits osteosarcoma cell infiltration and migration, while its overexpression increases both infiltration and migration." (PMID 36316642, 2022). "STEAP2 expression in osteosarcoma, osteofibrous dysplasia, and paratumoral tissues was evaluated using IHC, which revealed that STEAP2 was overexpressed in most osteosarcoma tissues but showed a low expression in osteofibrous dysplasia and paratumoral tissues." (PMID 36316642, 2022). "STEAP2 expression in peritumoral tissues, osteosarcoma, benign fibrous dysplasia, osteosarcoma cells, normal osteoblastic hFOB cells, and various invasive subclones was evaluated using IHC, ICC, and qRT-PCR." (PMID 36316642, 2022). "Taken together, these data suggest that EFEMP2 induces EMT and initiates the PI3K/Akt/mTOR axis partly via its interaction with STEAP2, thereby enhancing the migratory and invasive capacities of osteosarcoma cells and promoting the development of osteosarcoma." (PMID 36316642, 2022). "The increased expression was largely localized to the cytoplasm of the osteosarcoma cells, and STEAP2 expression displayed little variation across the various pathological subgroups of this disease." (PMID 36316642, 2022). "These assays revealed STEAP2 mRNA and protein expression in both osteosarcoma (U-2OS and MG63) and normal osteoblastic (hFOB) cell lines, with increased expression in the U-2OS and MG63 cell lines." (PMID 36316642, 2022). "In this study, we clearly show that changes in EFEMP2 expression directly affect STEAP2 expression in osteosarcoma." (PMID 36316642, 2022). "STEAP2 is also overexpressed in highly invasive osteosarcoma and subclone cell lines, and similar to EFEMP2, it also induces EMT through the PI3K/AKT/mTOR axis." (PMID 36316642, 2022). "The assay results revealed that the introduction of the PI3K/AKT inhibitor reversed the enhanced invasiveness of these osteosarcoma cells and that these effects were concentration dependent, confirming the direct relationship between STEAP2 and the PI3K/AKT pathway." (PMID 36316642, 2022). "To date, there has been little investigation into the up- and downstream mechanisms controlling EFEMP2 and STEAP2 expression; however, this work suggests that these mechanisms may have a significant impact on the treatment of osteosarcoma." (PMID 36316642, 2022).
osteosarcoma (continued). "Thus, downregulation of STEAP2 or Akt blocks EFEMP2-mediated induction of the EMT process in osteosarcoma cells." (PMID 36316642, 2022). "Thus, we were able to conclude that STEAP2 inhibition is likely to reduce the proliferation, clonogenicity, infiltration, and migration of osteosarcoma cells, while its overexpression is likely to facilitate all of these outcomes." (PMID 36316642, 2022). "EFEMP2 is also likely to partly target STEAP2 to promote osteosarcoma progression." (PMID 36316642, 2022). "In addition, knockdown of STEAP2 reduces the proliferation, clonogenesis, infiltration, and mobility of osteosarcoma cells, whereas STEAP2 upregulation promotes proliferation, clonogenesis, mobility, and invasion in these cells." (PMID 36316642, 2022). "In addition, our data shows that the overexpression of this protein increases infiltration and migration and that EFEMP2 initiates the Akt pathway triggering EMT via its direct regulation of STEAP2, thereby intensifying the migratory and invasive capacities of osteosarcoma cells." (PMID 36316642, 2022). "Given that the relationship between STEAP proteins and osteosarcoma remains largely unknown, we used the data to develop a set of experiments designed to determine whether STEAP2 promotes the development of osteosarcoma and whether these functions are linked to EFEMP2 activity in these cells." (PMID 36316642, 2022). "Give this, we hypothesized that EFEMP2 is closely related to STEAP2, and further experimental results revealed that knockdown of STEAP2 expression in EFEMP2 cDNA-transfected osteosarcoma cells significantly reduced the increased invasive capacity conferred by EFEMP2 overexpression." (PMID 36316642, 2022). "Given these outcomes, this study mainly evaluated the roles of STEAP2 in osteosarcoma, its value as biomarker, and its specific interaction with EFEMP2, to better understand osteosarcoma pathogenesis." (PMID 36316642, 2022). "These experiments demonstrated that a reduction in either STEAP2 or Akt or both inhibited EMT and PI3K/Akt/mTOR axis activation in osteosarcoma cells even when treated with exogenous EFEMP2." (PMID 36316642, 2022). "Changes in EFEMP2 expression resulted in correlating changes in STEAP2 expression, with EFEMP2-overexpressing osteosarcoma cells exhibiting a less invasive phenotype and reduced EMT following STEAP2 inhibition." (PMID 36316642, 2022). "To our knowledge, this is the first study to explore the relationship between STEAP2 and osteosarcoma, and similar to EFEMP2 expression, we found that STEAP2 was also highly expressed in osteosarcoma and likely to affect EMT through the PI3K/AKT/mTOR axis." (PMID 36316642, 2022). "EMT is a key factor in oncocyte migration and invasion, and downregulation of STEAP2 represses EMT through reduced PI3K/AKT/mTOR axis activity, which in turn reduces osteosarcoma cell migration and infiltration." (PMID 36316642, 2022). "Our previous study revealed that EFEMP2 facilitates osteosarcoma infiltration and migration via its activation of the PI3K/Akt/mTOR axis and that changes in EFEMP2 expression induce similar changes in STEAP2 expression." (PMID 36316642, 2022). "In addition, STEAP2 expression induced epithelial–mesenchymal transition (EMT) via the PI3K/AKT/mTOR axis and facilitated osteosarcoma cell infiltration and migration." (PMID 36316642, 2022). "Moreover, upregulation of STEAP2 promotes EMT via activation of the PI3K/AKT/mTOR axis thereby enhancing the metastatic and invasive capabilities of osteosarcoma cells." (PMID 36316642, 2022). "It is also worth noting that although EFEMP2 overexpression activated the PI3K/AKT/mTOR pathway promoting EMT, it did not affect osteosarcoma cells in which STEAP2 or Akt was knocked down." (PMID 36316642, 2022).
osteosarcoma (continued). "Based on these experimental results, we hypothesize that osteosarcoma cells secrete excessive EFEMP2, which in turn targets STEAP2 initiating the PI3K/Akt/mTOR axis and inducing EMT which in turn enhances osteosarcoma cell infiltration and migration." (PMID 36316642, 2022). "Thus, we can conclude that STEAP2 acts as an oncogene in osteosarcoma progression, while EFEMP2 enables PI3K/AKT/mTOR axis initiation and EMT by partly targeting STEAP2, thereby facilitating osteosarcoma cell infiltration and migration." (PMID 36316642, 2022). "In addition, similar to EFEMP2, STEAP2 may induce EMT through the PI3K/AKT/mTOR axis and facilitate osteosarcoma cell infiltration and migration." (PMID 36316642, 2022). "Similarly, repression of STEAP2 reversed the effect of EFEMP2 overexpression, and exogenous EFEMP2 activated the Akt pathway and EMT process in osteosarcoma cells but had no impact on cells with reduced STEAP2 or Akt expression." (PMID 36316642, 2022).
prostate tumor (3 papers, 2021 to 2025). "Six-transmembrane epithelial antigen of prostate-2 (STEAP2) is a protein highly expressed by prostate tumor cells, and its use for targeting CAR T cells can be effective." (PMID 40607417, 2025). "First, STEAP2 displays an ideal expression profile for targeting as compared with many other prostate tumor antigens due to limited distal normal tissue expression, as evaluated by IHC, the Human Protein Atlas, and proteomic data sets." (PMID 37966111, 2023). "Next, we developed a STEAP2-specific rabbit polyclonal IHC reagent to evaluate the prevalence and localization of protein expression in broad tissue microarrays (TMAs), where high, homogeneous expression levels were found to be restricted to prostate tumors." (PMID 37966111, 2023). "Considering the immunosuppressive nature of TGF-β, we undertook a series of studies to investigate the feasibility of targeting the STEAP2 prostate antigen with CAR-Ts that were armored to withstand the TGF-β–rich immunosuppressive environment found in prostate tumors." (PMID 37966111, 2023).
colon cancer (2 papers, 2020 to 2022). "Besides, STEAP2 was also highly expressed in colorectal cancer and drives the excessive proliferation of colon tumor cells." (PMID 32802887, 2020).
lung adenocarcinoma (2 papers, 2022 to 2024). A carcinoma that arises from the lung and is characterized by the presence of malignant glandular epithelial cells. "For lung adenocarcinoma, the level of STEAP1 and STEAP2, which have the ability to reduce Fe(3+) to Fe(2+) and stimulate the cellular iron uptake, were negatively related to prognosis of patients based on multiple databases." (PMID 38602575, 2024).
prostate adenocarcinoma (2 papers, 2023 to 2025). "Interestingly, canonical prostate adenocarcinoma cell-surface targets KLK2 and STEAP1 had significantly lower expression in the LumB versus LumA samples, and STEAP2 also had a trend toward lower expression in LumB, in contrast to FOLH1, which was highly expressed in both luminal CTC phenotypes." (PMID 39912912, 2025).
esophageal tumors (1 paper, 2022). "The “amplification” type was the primary type in most tumors, and the highest alteration frequency of STEAP2 (>10%) occurred in patients with esophageal tumors with “amplification” as the primary type." (PMID 36060273, 2022).
iron overload (1 paper, 2022). "Alternatively, Zip8 and Steap2 iron importers can take the role of DMT-1 in iron uptake of brain cells as they are not under the regulation of IRPs and may contribute to the increased intracellular iron content causing iron overload." (PMID 36210435, 2022).